HSPA1A (heat shock protein family A (Hsp70) member 1A)
Diseases named in the same sentence as HSPA1A in open-access papers (continued):
Sharing a sentence is not in itself a finding about the gene and the disease.
lung carcinoma (11 papers, 2017 to 2025). "Treatment with an HSPA1A inhibitor could significantly inhibit the malignant progression of lung cancer with ARID2 deficiency." (PMID 34858604, 2021). "Furthermore, HspA1A specifically inhibits the malignant progression of Arid2-deficient lung cancer." (PMID 35887223, 2022). "Strong evidence suggests that HSPA1A is overexpressed in various tumors, such as lung cancer, gastric cancer, and GBM, and promotes tumor proliferation, metastasis, and drug resistance." (PMID 34307121, 2021). "HSP90AA1 and HSPA1A were detected at the surface of tumor cell lines (microcitoma, lung carcinomas, melanomas, Ewing’s sarcomas, osteosarcomas and hepatomas)." (PMID 28468249, 2017). "However, given that lung cancers secrete multiple additional factors (e.g., HSPA1A, MFGE8, ANXA4), our approach allows us to study and dissect the role of tumor‐derived EVs independent of other secreted factors." (PMID 40788065, 2025). "EIF3C overexpression may facilitate the proliferation and hamper the apoptosis of lung cancer cells by regulating the APP/HSPA1A/LMNB1 axis." (PMID 36157221, 2022). "Nevertheless, whether EIF3C promotes lung cancer tumorigenesis by regulating HSPA1A via the PI3K/AKT pathway warrants further investigation." (PMID 36157221, 2022). "Knockdown of Hspa1a specifically inhibits malignant progression of Arid2-deficient but not Arid2-wt lung cancers in both cell lines as well as animal models." (PMID 34858604, 2021). "HSPA1A is upregulated in CD4+ and CD8+ T cells after treatment with immune checkpoint blockers in various cancers, such as renal cancer, lung cancer, and basal cell carcinoma." (PMID 37762493, 2023). "Besides, it has been proposed that HSPA1A (HSP70), a chaperone molecule, is strongly involved in promoting and development of different tumor cells and overexpression of this heat-shock protein has been shown to be associated with the progression of several tumors such as lung cancer." (PMID 33765916, 2021). "In lung cancer, the expression of HSP70 was studied before, another HSP70 family member also known as HSPA1A or HSP70-1." (PMID 33029283, 2020). "In summary, we suggested for the first time that EIF3C is upregulated in lung cancer tissues and may enhance the proliferation and suppress the apoptosis of lung cancer cells by regulating the APP/HSPA1A/LMNB1 axis." (PMID 36157221, 2022).
melanoma (10 papers, 2013 to 2025). A malignant, usually aggressive tumor composed of atypical, neoplastic melanocytes. "Studies indicated that HSPA1A is released from melanoma cells in both a soluble form and within vesicles, effectively sensitizing these tumor cells to NK cell cytolytic activity." (PMID 41369326, 2025). "In a preclinical study, human melanoma-derived exosomes containing and transferring heat shock 70 kDa protein 1A (HSPA1A) and full-length tumor antigens to DCs induced CD8+ T cell cross-priming and tumor rejection." (PMID 33168028, 2020). "We demonstrate that MB-treatment attenuates thermally- and pharmacologically-induced heat shock response gene expression, suppressing Hsp70 (HSPA1A) and Hsp27 (HSPB1) upregulation at the mRNA and protein level, and causing chemosensitization of melanoma cells to geldanamycin cytotoxicity." (PMID 23429201, 2013). "For the malignant melanoma cells, PMEL, IFITM1, HSPA1A, DUSP1, FOS and TMSB4X are the shared driver genes across three subtypes in S4 File." (PMID 38096269, 2023). "Another example is methylene blue which showed suppression of HSPA1A and HSPB1 induction and sensitized melanoma cells to other chemotherapeutics." (PMID 35311075, 2022).
ovarian cancer (7 papers, 2012 to 2025). A primary or metastatic malignant neoplasm involving the ovary. "Previous studies showed that HSPA1A was decreased in ovary cancer, and downregulation of HSPA1A was related to increased methylation." (PMID 34765552, 2021). "The intracellular location of HspA1A was detected in OC cells from examined tumor specimens, as well as in ovarian cancer cell lines." (PMID 22528050, 2012). "The participation of TLR2 and TLR4 expressed on neutrophils in the interaction via HspA1A with ovarian cancer cells was also investigated." (PMID 22528050, 2012). "The main aim of our research was to recognize the molecular mechanism of ovarian cancer cells action on autologous neutrophils in respect to the interaction of HspA1A with TLR2/4." (PMID 22528050, 2012). "In this study, we have shown that membrane-bound HspA1A was expressed on nearly 80 % of OC cells isolated from tumor specimens of all tested ovarian cancer patients." (PMID 22528050, 2012). "Herein, we demonstrate that a recombinant vaccinia virus armed with HSPA1A-targeting shRNA (oncoVV-shHSP70) dismantles ovarian cancer cells by enhancing autophagic flux and triggering an autophagy–ROS feedback loop, which then promotes inflammatory cytokine expression and viral replication." (PMID 41305448, 2025). "The increase in HSPA1A was correlated to poor prognosis of ovary cancer." (PMID 34765552, 2021). "Moreover, the Hsp70 homolog, HSPA1A, was found both through microarray analysis and text mining, in this study, to be overexpressed in ovarian cancer, as well as lung carcinoma according to a previous study." (PMID 31814876, 2019). "HSPA1A was also recently found to be hypermethylated in ovarian cancer cells." (PMID 23874968, 2013). "The aim of this study was to examine whether HspA1A membrane-bound and/or released from ovarian cancer cells could be involved in the activation of neutrophils of patients with advanced ovarian cancer." (PMID 22528050, 2012). "Currently, our study demonstrates for the first time that activation of ovarian cancer patients’ neutrophils by ovarian cancer cells is dependent on the interaction of HspA1A originating from ovarian cancer cells, with TLR2 and TLR4 expressed on the surface of neutrophils." (PMID 22528050, 2012). "We also observed downregulation of key HSPs including Hspa1a, Hspa1b, and Dnajb1 upon Ier5 knockdown in HM-1 and MOV ovarian cancer cells." (PMID 40002205, 2025). "We and others found that ovarian cancer cells isolated from both tumors, as well as ovarian cancer cell lines A2780, SK-OV-3, and OVCAR-3, released HspA1A outside cells." (PMID 22528050, 2012).
hepatocellular carcinoma (6 papers, 2017 to 2024). A malignant tumor that arises from hepatocytes. "As a ligand for TLR2 and TLR4, extracellular HSPA1A potently stimulates proliferation and inhibits apoptosis in hepatocellular carcinoma cells via TLR2 and TLR4 signaling pathway and activation of nuclear factor-κB (NF-κB)." (PMID 38646439, 2024). "For instance, HSPA1A promotes hepatoma cell proliferation through TLR2 and TLR4 signaling pathways, and HSPA1L/HIF-1 α/GP78 significantly influences tumor progression." (PMID 34059060, 2021). "Recently, single-cell profiling analysis of human CD127+ innate lymphoid cells from human patients with hepatocellular carcinoma (HCC) revealed that HSPA1A and HSPA1B expression were highly activated in late-state HCC, suggesting HSPA1B is important in tumor microenvironment remodeling." (PMID 38786053, 2024). "Furthermore, we found significant differences in clinicopathological characteristics (age, gender, fibrosis Ishak score, pathologic T, and race) between HSPA1A, NR1I3, PPARGC1A, and MAT1A gene expressions and hepatocellular carcinoma patients." (PMID 37993485, 2023). "Tumor cell lines, such as hepatocellular carcinoma cell line HepG2 and murine leukemia monocytes cell lines, were described to secrete HSPD1, HSPA1A, and HSP90AA1 in exosomes, which augmented the cytolytic activity of natural killer cells, macrophages and mononuclear cells." (PMID 28468249, 2017).
schizophrenia (6 papers, 2017 to 2025). A major psychotic disorder characterized by abnormalities in the perception or expression of reality. "We also identified C–G–T haplotype as predisposing to schizophrenia, and demonstrated the effects of HSPA1A and HSPA1B genotypes on psychopathology and age of onset." (PMID 31642026, 2020). "The obtained results provided the first evidence that the HSPA1A + 190CC genotype and + 190C allele may potentially confer increased risk for paranoid schizophrenia in Caucasian Polish residents in a sex-dependent manner." (PMID 31642026, 2020). "In a previous study, we observed that sex might modulate the risk that is conferred by the HSPA1A rs1043618 polymorphism for SCZ as females with the rs1043618 genotype have a two-fold greater risk of developing schizophrenia than males carrying the same genotype." (PMID 34932194, 2022). "Alterations of HSPA8 activity have been linked to both neurodegenerative and neuropsychiatric diseases, such as neuroaxonal dystrophy, schizophrenia, Parkinson’s and ALS, with both HSPA1A and HSPA8 associated with neuroprotection." (PMID 41465490, 2025). "The heat shock protein 70 (HSPA1A, increased in males) overlaps with the findings of a previous systematic review, highlighting the impairment of protein processing in schizophrenia." (PMID 39068467, 2024). "The genes encoding HSPA1A, HSPA1B, and HSPA1L are located in the MHC class III region of 6p21.3–22.1, which is a region implicated in susceptibility to schizophrenia." (PMID 35562887, 2022). "In our previous work, we explored the possibility that HSPA1A (+190G/C), HSPA1B (+1267A/G), and HSPA1L (+2437T/C) gene polymorphisms might be involved in the susceptibility to paranoid schizophrenia and clinical presentation of the disease in the Polish population." (PMID 31642026, 2020).
colorectal cancer (5 papers, 2020 to 2025). A primary or metastatic malignant neoplasm that affects the colon or rectum. "Among these, genes with positive coefficients (ABHD4, ABHD8, YJEFN3, CRYAB, and HSPA1A) were found to be risk factors, suggesting that their increased expression is associated with worse prognoses in colorectal cancer patients." (PMID 41293172, 2025). "For example, increased expressions of the members of the HSP70 family HSPa1a, HSPa1b, and HSPa7 are associated with a poor prognosis in human colorectal cancer observed in the comparison of the pretreatment tumor samples with the clinical data." (PMID 35681533, 2022). "Another study indicated that HSPA1A was decreased in colorectal cancer and high HSPA1A was related to poor survival." (PMID 34765552, 2021).
COVID-19 (5 papers, 2020 to 2025). A disease caused by infection with severe acute respiratory syndrome coronavirus 2. "Specifically, the polymorphic variants rs1136141 and rs1461496 HSPA8, rs1042665 HSPA9, rs7189628 DNAJA2, rs910652 HSPA12B, rs6457452 HSPA1B and rs1043618 HSPA1A are associated with alerted risk of severe COVID-19." (PMID 41009536, 2025). "These genes were used as identifiers to classify the 126 patients based on the random forest algorithm, revealing that CD38, PTX3, and HSPA1A were able to classify patients into the correct groups and contribute specifically to COVID-19." (PMID 34899651, 2021). "Notably, two SNPs rs1136141 HSPA8 and rs7189628 DNAJA2 are associated with severe COVID-19 in patients under 68 years of age, whereas in older patients, SNPs rs1461496 HSPA8, rs910652 HSPA12B, rs1043618 HSPA1A and rs6457452 HSPA1B are significantly associated with severe disease." (PMID 41009536, 2025). "Regardless of the tissue type, we saw consistent increases in genes such as B2M, CD81, GNAS, HLA.B, HSPA1A, HSPB1, and SERPING1 in COVID-19 lungs." (PMID 35233546, 2022). "A large body of scientific evidence now indicates that the accumulation of cellular HSP70s, especially HSPA1A, in lung alveolar cells is beneficial against ARDS-induced lung damage, as in the case of the most severe COVID-19 pathologies." (PMID 33043037, 2020).
glioblastoma (5 papers, 2016 to 2024). The most malignant astrocytic tumor (WHO grade IV). "The major stress-inducible protein Hsp70 (HSPA1A) is overexpressed in the cytosol of many highly aggressive tumor cells including glioblastoma multiforme and presented on their plasma membrane." (PMID 32276468, 2020). "In this study, we chose the intracranial C6 rat glioblastoma model and found that the depletion of Hsp70 (HSPA1A) via lentiviral constructs delayed tumor growth, whereas the inhibition of Hdj1 resulted in no changes in tumor development." (PMID 26959111, 2016). "To analyze whether this also functions in a highly malignant brain tumor, we knocked down the expression of Hsp70 (HSPA1A) and its two most abundant co-chaperones, Hdj1 (DNAJB1) and Hdj2 (DNAJA1) in a C6 rat glioblastoma cell line." (PMID 26959111, 2016).
Obesity (5 papers, 2015 to 2023). Accumulation of substantial excess body fat. "Hspa1b, a close relative of Hspa1a, was associated to obesity, type 2 diabetes mellitus, and hyperlipidemia." (PMID 28425976, 2017). "It has been reported that the expression of HSPA1A/HSPA1B (HSP70/HSP 72) was decreased by obesity, insulin resistance, and ageing." (PMID 37238736, 2023).
psoriasis (5 papers, 2024 to 2025). An autoimmune condition characterized by red, well-delineated plaques with silvery scales that are usually on the extensor surfaces and scalp. "This study announced that AIF1, FCGR3, and HSPA1A were the unexplored but material variants of psoriasis, thus providing novel and valuable targets for psoriasis treatment and broadening new orientation of drug development for psoriasis." (PMID 39883516, 2024). "PheWAS indicated that high levels of HSPA1A may raise the risk of celiac disease and MS, yet act as a protective factor against RA and psoriasis." (PMID 38997544, 2024). "Based on the GWAS data, further MR analysis and colocalization analysis genetically predicted that AIF1, FCGR3A, NEU1, HSPA1A, TNXB (Tenascin XB), and ABO were associated with psoriasis risk." (PMID 39883516, 2024). "Combined with the protein target druggability, mouse KO models, and PPI network, FCGR3A, AIF1, and HSPA1A were highlighted for functioning as potential targets for psoriasis with strong evidence." (PMID 39883516, 2024). "P. clypearia may ameliorate inflammation in psoriasis mice by modulating genes such as Hspa1a, Hspa1b, mt-Nd4l, mt-Nd5, mt-Nd6, Bcl2, Asns, Trib3, and associated pathways related to energy metabolism, cell growth, and apoptosis." (PMID 41385507, 2025). "In addition, AIF1, FCGR3A, and HSPA1A have been finally determined to be feasible therapeutic targets for psoriasis after being confirmed by druggability verification and specific mouse knock-out models." (PMID 39883516, 2024). "MR analyses unveiled 19 unique circulating proteins that were associated with psoriasis, among which only AIF1, FCGR3A, NEU1, HSPA1A, TNXB, and ABO were the potential proteins that interacted with psoriasis risk after being analyzed with high evidence of colocalization (PP.H4 > 0.9)." (PMID 39883516, 2024). "AIF1 (allograft inflammatory factor 1), FCGR3, and HSPA1A [shock protein family A (Hsp70) member 1A] were finally identified as novel and valuable targets for psoriasis treatment, broadening new possible orientations of drug development for psoriasis." (PMID 39883516, 2024). "Although the association between psoriasis and HSPA1A has not been reported, our findings suggest that HSPA1A may be a potential therapeutic target for psoriasis for the following reasons." (PMID 39883516, 2024). "In addition, HSPA1A has been verified as another target in psoriasis." (PMID 39883516, 2024). "The results indicated that P. clypearia may affect the energy metabolism, cell growth and apoptosis by regulating genes such as Hspa1a, Hspa1b, mt-Nd4l, mt-Nd5, mt-Nd6, Bcl-2, Asns, Trib3, GzmA, CTSG, etc, thereby mitigating psoriasis-related inflammation." (PMID 41385507, 2025). "Besides, our PPI network showed that HSPA1A has a significant correlation with NR3C1, a known target of psoriasis." (PMID 39883516, 2024).
Stroke (5 papers, 2013 to 2025). Sudden impairment of blood flow to a part of the brain due to occlusion or rupture of an artery to the brain. "Most upregulated genes acutely after stroke were as expected early-response and inflammation associated genes such as Hspa1a, Cxcl1, Ccl3, and Fos." (PMID 37337154, 2023). "In consistency with other studies, our results revealed that several heat stroke proteins, including HMOX1, Hspa1a and Hp, were significantly up-regulated after heat exposure." (PMID 32436952, 2020). "Given that Hspa1a and Hspa1b were the most upregulated genes in the post-ischemic endfoot translatome, we asked whether their protein product, inducible HSP70, was more abundant in endfeet after stroke." (PMID 39796165, 2025).
type 2 diabetes mellitus (5 papers, 2015 to 2020). A type of diabetes mellitus that is characterized by insulin resistance or desensitization and increased blood glucose levels. "Several studies have already revealed the significant role of HspA1A (Hsp72) in the prevention of hyperinsulinemia and insulin resistance both in animal models of type 2 diabetes mellitus and in human type 2 diabetic patients." (PMID 30336561, 2018). "Research on the involvement of chaperones in the pathogenesis of type 2 diabetes mellitus has documented the role of HspA1A (Hsp72) in the prevention of β-cell mass decline, suppression of inflammation, and attenuation of insulin resistance, especially in the context of obesity or a high-fat diet." (PMID 30336561, 2018).
atherosclerosis (4 papers, 2017 to 2023). A disease characterized by the build-up of fatty material and calcium deposition in the arterial wall resulting in partial or complete occlusion of the arterial lumen. "It has been shown that HSPA1A can protect against atherosclerosis because of its anti-inflammatory and antithrombotic characteristics." (PMID 37180137, 2023). "Heat shock proteins were also found to be present as extracellular proteins, and concentrations of these have been found to vary in many conditions, including HSPB1 and HSPA1A in cancer, cardiovascular disease, HSPB1 in atherosclerosis and HSPA1A in rheumatoid arthritis." (PMID 37583307, 2023). "Further, enrichment of genes in disease ontology revealed that the Hspa1a gene was related to multiple CVD indications such as coronary disease, atherosclerosis, and acute coronary syndrome, as well as disease progression of systolic heart failure." (PMID 28425976, 2017).
bladder cancer (4 papers, 2013 to 2023). "The differential expression of HSPA1A in the four bladder cancer cell lines tested was associated with differential binding of HSF1 to the HSPA1A promoter, which was due to HSPA1A promoter methylation in the UM-UC10 and UM-UC13 cells." (PMID 23874968, 2013). "They conducted an in vitro experiment on bladder cancer cell lines, demonstrating that BTZ-resistant cells had a low expression of HSPA1A which was associated with the revealed hypermethylation of the HSPA1A promoter." (PMID 38201512, 2023). "UM-UC10 and UM-UC13 bladder cancer cells express HSPA1A mRNA at a very low level, and treatment with the DNA methyltransferase inhibitor 5-aza-2′-deoxycytidine (Aza) restored HSPA1A expression." (PMID 31557887, 2019). "Hypermethylation of the HSPA1A promoter has been reported in human ovarian and bladder cancer cells." (PMID 31557887, 2019). "In preliminary experiments we have determined that HSPA1A is also methylated in approximately half of primary human bladder cancers (W. Qi, unpublished observations)." (PMID 23874968, 2013). "Developing strategies to specifically inhibit HSPA1B could produce synthetic lethality in bladder cancers and other tumors with HSPA1A methylation." (PMID 23874968, 2013). "However, an attractive explanation is that the HSPA1A gene lies in a particularly vulnerable CpG island that is targeted incidentally as a result of the more global methylation changes that drive bladder cancer cancer progression." (PMID 23874968, 2013).